FGFR2 (fibroblast growth factor receptor 2)
Diseases named in the same sentence as FGFR2 in open-access papers (continued):
Sharing a sentence is not in itself a finding about the gene and the disease.
Crouzon syndrome (continued). "We evaluate the embryonic mouse chondrocranium and dermatocranium in 3D, and delineate the effects of a Fgfr2 variant on embryonic chondrocranial cartilages and on their association with forming dermal bones using the Fgfr2cC342Y/+ Crouzon syndrome mouse." (PMID 35704354, 2022). "We further detected low-grade mosaicism for a variant in the FGFR2 gene in a healthy parent of two children with Crouzon syndrome and for a deletion (including the TWIST1 gene) in a healthy father of a child with Saethre–Chotzen syndrome." (PMID 33288889, 2021). "Our study confirms the presence of optic nerve atrophy in patients with Crouzon syndrome carrying FGFR2 C342W mutations and indicates that MRI and funduscopy should be performed to examine the optic nerve changes for patients with Crouzon syndrome." (PMID 33725872, 2021). "In this study, we investigated the levels of mRNA and protein expression related to cellular differentiation of Crouzon syndrome patient‐derived DPSCs (CS‐DPSCs) with a Gly338Arg fibroblast growth factor receptor 2 mutation." (PMID 33386632, 2021). "Here we report the detection of FGFR2 mutation and its related clinical findings in 2 patients with Crouzon syndrome from a Chinese family." (PMID 33725872, 2021). "Another important hereditary disease was Crouzon syndrome which is an autosomal dominant craniosynostosis disorder which is caused by mutation in the Fibroblast Growth Factor Receptor 2 (FGFR2) genes." (PMID 32962661, 2020). "Mutations in FGFR2 are associated with over ten distinct diseases including Pfeiffer syndrome and Crouzon syndrome." (PMID 32019583, 2020). "Crouzon syndrome is most commonly caused by a point mutation in exon 9 of the FGFR2 gene, is autosomal dominantly inherited and exclusively affects the IIIc isoform." (PMID 30266836, 2018). "Apert and Crouzon syndromes are caused by mutations in FGFR2 that increase affinity of the receptor for the ligand, and Pfeiffer syndrome is caused by mutations in either FGFR2 or FGFR1." (PMID 30505318, 2018). "In particular, mice homozygous for an activating mutation in FGFR2 (W290R), mimicking human Crouzon syndrome, exhibit thickened cartilage underlying the cranial bones." (PMID 29752281, 2018). "It appears that the clinical spectrum in patients with dominant (heterozygous) mutations in FGFR2 is reflected by the complete range (i.e. wild-type→heterozygote→homozygote) in the mouse model for Crouzon syndrome." (PMID 28069589, 2017). "In approximately 80% of Crouzon syndrome and PS, the mutation is located in the exon 8 and 10 of FGFR2, which encode the third immunoglobulin-like domain of the protein (IgIII), but mutations in different exxons have also been identified." (PMID 25129254, 2015). "Crouzon syndrome is typically caused by heterozygous missense mutations in the third immunoglobulin domain of FGFR2." (PMID 25174698, 2014). "It is known that Crouzon syndrome is usually caused by mutations in the fibroblast growth factor receptor 2 (FGFR2) gene, located on chromosome 10q26." (PMID 22665975, 2012). "In this study, we found one mutation in exon 8 of the FGFR2 gene that is associated with Crouzon Syndrome: c.866A>C." (PMID 22355256, 2012). "Although FGFR2 mutations and polymorphisms have been reported in various ethnic groups, especially in the area of osteology, we report, for the first time, the identification of one new FGFR2 mutation in Chinese patients with Crouzon syndrome." (PMID 22355256, 2012). "In summary, this study identified one novel mutation of FGFR2 in a Chinese family with Crouzon syndrome." (PMID 22355256, 2012). "It is known that Crouzon syndrome is usually caused by mutations in the FGFR2 gene located on chromosome 10q26." (PMID 22355256, 2012). "In this study, we found one mutation in exon 10 of FGFR2 that is associated with Crouzon Syndrome: c.1030G>C." (PMID 22665975, 2012).
Crouzon syndrome (continued). "Although FGFR2 mutations and polymorphisms have been reported in various ethnic groups, especially in the area of osteology, we report, for the first time, the identification of one new FGFR2 gene mutation in Chinese patients with Crouzon syndrome." (PMID 22665975, 2012). "Here we describe the first molecularly documented evidence of germline and somatic mosaicism for FGFR2 mutation, identified in the mother of a child with Crouzon syndrome caused by a heterozygous c.1007A>G (p.Asp336Gly) substitution." (PMID 20635358, 2010). "FGFR2 mutations lead to various syndromic craniosynostoses characterized by the fusion of coronal or multiple sutures, including Crouzon, Apert, Pfeiffer, and Beare–Stevenson syndromes, with Crouzon syndrome being the most common." (PMID 41390905, 2025). "Similarly, other craniosynostosis disorders that result in strabismus, such as Crouzon syndrome and Pfeiffer syndrome, have gain-of-function mutations in FGFR2." (PMID 40894678, 2025). "The Fgfr2cC342Y/+ Crouzon syndrome mouse model carries a cysteine to tyrosine substitution at amino acid 342 (Cys342Tyr; C342Y) in the protein encoded by Fgfr2c equivalent to the FGFR2 variant common to Pfeiffer and Crouzon syndromes." (PMID 35704354, 2022). "The Fgfr2cC342Y/+ Crouzon syndrome mouse model carries a cysteine to tyrosine substitution at amino acid position 342 (Cys342Tyr; C342Y) in the fibroblast growth factor receptor 2 (Fgfr2) gene equivalent to a FGFR2 mutation commonly associated with Crouzon and Pfeiffer syndromes in humans." (PMID 35651944, 2022). "We describe a FGFR2 mutation (p.G338R, c.1012G > C) in a Chinese family with Crouzon syndrome." (PMID 29848297, 2018). "The weak findings in this study provide little support for mutation of FGFR2 may lead to reduce the volume of orbit in Crouzon syndrome patients." (PMID 29848297, 2018). "However, few reports are available quantifying the orbital volume of Crouzon syndrome and there was little direct evidence to show FGFR2 mutation actually influencing orbital morphology." (PMID 29848297, 2018). "Our study further identified G338R FGFR2 mutation (c1012G > C) lead to inherited Crouzon syndrome." (PMID 29848297, 2018). "Furthermore, through chorionic villus biopsy, Schwartz using PCR by targeting of FGFR2 known mutation found within the pregnant mother, successfully demonstrated diagnosis of the pregnancy Crouzon syndrome." (PMID 29848297, 2018). "We find that the homozygous mutants represent the most severe end of the phenotypic spectrum, which has allowed us to study the causative molecular events and improve the understanding of the pathogenesis of Crouzon syndrome and related craniofacial birth defects caused by mutation of FGFR2." (PMID 28069589, 2017). "Crouzon's syndrome is caused by mutation in the fibroblast growth factor receptor 2 (FGFR2) gene." (PMID 28127173, 2016). "Mutations in Fgfr2 cause Apert, Crouzon, Jackson-Weiss, and Pfeiffer craniosynostosis syndromes, while mutations in Fgfr1 cause Pfeiffer syndrome and mutations in Fgfr3 cause Muenke craniosynostosis syndrome and Crouzon syndrome with acanthosis nigricans." (PMID 23762837, 2013). "Similarly, due to the gain-of-function mutation in FGFR2, Crouzon syndrome arises." (PMID 35455561, 2022). "Further research could explore how FGFR2 gene can cause shallow orbits in Crouzon syndrome." (PMID 29848297, 2018). "Crouzon syndrome is considered as a very unique single-gene defect disease, primarily involving FGFR2." (PMID 36755349, 2023). "Fibroblast growth factor receptor 2 (FGFR2) is considered as the genetic etiology of Crouzon syndrome." (PMID 36231091, 2022). "At the age of 5 she had the first genetic consultation at our clinic and on that occasion, following clinical suspicion of Crouzon syndrome, mutation screening of the FGFR1 and FGFR2 genes was performed through the dHPLC technique, with normal results." (PMID 35885943, 2022).
Crouzon syndrome (continued). "Crouzon syndrome, with an estimated birth prevalence of 16.5/1,000,000 is possibly the mildest of FGFR2 craniosynostosis syndromes." (PMID 35651944, 2022). "The Crouzon syndrome (CS) is an autosomal dominant genetic disease caused by mutations in one of the FGFR (fibroblast growth factor) genes, especially the FGFR2, which is responsible for the early closure of the cranial sutures." (PMID 35053637, 2021). "In this manuscript, we have attempted to identify the gain-of-function role of G338R FGFR2 (c.1012G > C) potentially related to shallow orbits even premature suture closure in Crouzon syndrome patient." (PMID 29848297, 2018). "A plot of the first two principal axes of the PCA reveals that brain shape of Fgfr2cC342Y/+ Crouzon syndrome mice and unaffected littermates separate along PC1, though the brains of two unaffected littermates cluster with the mice carrying the Fgfr2 mutation." (PMID 28790902, 2017). "In this study, we identified novel phenotypic features in a mouse model for Crouzon syndrome and were able to show that FGFR2 plays a role in the early patterning of skeletal tissues by regulating the process of mesenchymal condensation." (PMID 28069589, 2017). "The purposed of this study was to investigate the fibroblast growth factor receptor 2 (FGFR2) gene in one Chinese family with Crouzon syndrome and to characterize the related clinical features." (PMID 22355256, 2012). "The purpose of this study was to investigate the fibroblast growth factor receptor 2 (FGFR2) gene in three Chinese patients with Crouzon syndrome and to characterize the related clinical features." (PMID 22665975, 2012). "In addition to FGFR2, FGFR3 mutation is thought to be related to Crouzon syndrome with acanthosis nigricans ((OMIM) #612247)." (PMID 36231091, 2022). "In this study, we detected the FGFR2 mutation (p.Cys342Arg) with no experiment proof ever in two Chinese sporadic patients with Crouzon syndrome." (PMID 36231091, 2022). "Here, we analyzed the impact of Fgfr2- and Fgfr3-activating mutations on mandibular bone formation and endochondral bone repair after non-stabilized mandibular fractures in mouse models of Crouzon syndrome (Crz) and hypochondroplasia (Hch)." (PMID 39837840, 2025). "In this study, we found the new underlying mechanism whereby FGFR2 mutation p.Cys342Arg enhances mitochondrial metabolism-mediated osteogenesis through the FGF/FGFR-AMPK-Erk1/2 axis in Crouzon syndrome, which may provide a new adjuvant therapy for treating Crouzon syndrome." (PMID 36231091, 2022).
lung cancer (62 papers, 2007 to 2026). A malignant neoplasm involving the lung. "In previous reports, FGFR3 expression was associated with lung cancer, whereas FGFR2 played an important role in alveolar epithelial cell homeostasis and survival following injury." (PMID 38916962, 2024). "Activating mutations in FGFR1 were found in glioblastoma, FGFR2 is often mutated in endometrial carcinomas and lung cancers, FGFR3 mutations are frequently found in bladder tumors and melanoma, whereas FGFR4 is mutated in endometrial and lung cancers." (PMID 30577533, 2018). "The lung cancer activating mutations in FGFR2 include W290C, E471Q, T787K, and kinase domain mutations K660E and K660N." (PMID 24817905, 2014). "We found the increased expression in FGFR2 is associated with poor outcome of stage I lung cancer patients." (PMID 22292069, 2012). "The gene FGFR2 (fibroblast growth factor receptor 2) is known to be involved in various cancer types and low gene expression measurements have been reported as linked to a shorter survival in lung cancer." (PMID 21401964, 2011). "The Sanger group also found two other somatic mutations in genes that encode the related family members, FGFR1 and FGFR2, in lung cancer specimens." (PMID 17487277, 2007). "Together, these findings suggest that Lrp1b and/or Fgfr2 may be linked to the propensity of tumor formation in the A/J mouse model of lung cancer." (PMID 35295134, 2021). "Aberrant activation of FGF receptor 2 (FGFR2) signaling through overexpression of FGFR2 and/or its ligands, mutations, or receptor amplification has been reported in multiple cancer types, including gastric, colorectal, endometrial, ovarian, breast and lung cancer." (PMID 29420662, 2018). "In contrast, the FGFR2-intergenic fusion in lung cancer produced a novel chimeric transcript with a complete kinase domain (FGFR2-PLEKHA4, E17: E10)." (PMID 41092072, 2025). "In the GH electronic database, FGFR2/3 fusions were more frequently seen in lung adenocarcinomas as compared to other histological lung cancer subtypes." (PMID 35566609, 2022). "Another study showed that erdafitinib and anti-PD-1 combination treatment induced changes in the tumour microenvironment to enhance antitumour response and survival in an FGFR2-mutant lung cancer mouse model." (PMID 34068816, 2021). "Comprehensive analysis of genomic alterations in SqCC have found that mutations in FGFR2 and FGFR3 are present in ~3% of cases and account for the most frequent somatic mutations in this lung cancer subtype." (PMID 34068816, 2021). "Transient receptor potential ankyrin 1 (TRPA1) is an ion channel that drives brain metastasis of lung cancer by activating fibroblast growth factor receptor 2 (FGFR2)." (PMID 32761606, 2021). "For example, FGFR2 was identified as an oncogene for the lung cancer based on the observation that the W290G mutant can promote lung cancer by stimulating growth factor signaling." (PMID 23472150, 2013). "Here we report on a spectrum of driver genes, including EGFR, KRAS, c-Met, PIK3CA, BRAF, STK11, PTEN, EML4-ALK fusion gene, DDR2, and FGFR2 in a population of Chinese patients with primary lung cancer." (PMID 22768234, 2012). "FGFR2 expression is also related to the stage in lung cancer and idiopathic pulmonary fibrosis." (PMID 38071755, 2023). "For example, KL expression has been shown to exert a protective effect against overall mortality in non-diabetic, pre-dialysis chronic kidney disease, whereas FGFR2 expression was associated with increased risk of poor prognosis in patients with IPF and lung cancer." (PMID 37035748, 2023). "The protein encoding this gene (FGFR2) is a member of the fibroblast growth factor receptor family (FGFR), which is involved in a wide array of pathways known to play a significant role in cell proliferation and cancer including lung cancer." (PMID 32244494, 2020). "Tyrosine kinase FGF receptor FGFR2 was found to be overexpressed in bladder and lung cancer." (PMID 31781300, 2019).
lung cancer (continued). "Mutations in FGFR2 and FGFR3 have also been reported in other tumor forms, whereas activation of FGFR1 has mainly been observed in the form of FGFR1 amplification in breast and lung cancer." (PMID 29159601, 2018). "Given the low mutation rate of FGFR2 in the lung cancer, down-regulation of the wild-type FGFR2 may compromise cell differentiation and promote cancer in most patients of the lung cancer." (PMID 23472150, 2013). "However, we found that FGFR2, which participates in cell differentiation, was down-regulated and hypermethylated in lung cancer." (PMID 23472150, 2013). "A subsequent report, however, showed that FGFR2 expression is rather low in TRPA1-expressin lung cancer cells and that the TRPA1–FGFR2 interaction is likely to be a rare event in LUAD." (PMID 37174661, 2023). "In the replication analysis, we found some shared genes in two independent cohorts, such as FGFR2 for the breast–ovarian cancer pair and MAP3K1 for the breast–lung cancer pair." (PMID 36819030, 2023). "Two FGFR2–KIAA1598 fusions and other FGFR2 fusions with novel partners (CIT, ERC1, LZTFL1, POC1B, SORBS1, TP73, TXLNA) have been recently identified in a large cohort (n = 26054) of lung cancer patients." (PMID 32962091, 2020). "FGFR-2 protein has been reported to be over-expressed in NSCLC, while FGFR inhibition has recently been shown to block lung cancer growth both in-vitro and in-vivo." (PMID 27586635, 2016). "We recently showed rapid induction of FGFR2 and FGFR3 expression in lung cancer cell lines following treatment with EGFR-specific TKIs." (PMID 25946135, 2015). "Furthermore, when we screened 135 lung cancer and 1,182 other cancer cell lines, numerous cells that expressed high FGF2 or FGF9 showed relatively higher expression levels of FGFR1, FGFR2, or both." (PMID 37880373, 2023). "Although the FGFR2 alteration frequencies of the two lung cancer subtypes (LUSC and LUAD) were similar, LUSC had FGFR2 fusion, but LUAD did not." (PMID 33968743, 2021). "In our present study using lung cancer cell lines, FGFR1 is most abundant receptor of the four family proteins in afatinib-resistant clones of PC9, and there was no enhancement in expression of other FGFR family proteins FGFR2, FGFR3 and FGFR4." (PMID 25115383, 2014).